TERT (telomerase reverse transcriptase)
Diseases named in the same sentence as TERT in open-access papers (continued):
Sharing a sentence is not in itself a finding about the gene and the disease.
melanoma (continued). "Nagore and colleagues have shown that melanoma patients harboring these specific TERT promoter mutations, in combination with BRAF/NRAS mutations within their tumor tissue, have a significantly shorter disease free survival than patients without this combination." (PMID 29108273, 2017). "Importantly, using cfDNA WGS we were able to reveal non-coding mutations, including a pathogenic mutation in the TERT promoter that has been reported previously in melanoma." (PMID 29075515, 2017). "Our results suggest that the TERT ddPCR assay could prove useful as a companion diagnostic to predict treatment benefit and to monitor response in melanoma patients and could be extended to other malignancies." (PMID 29108273, 2017). "The first and most significant example of an oncogenic non-coding mutation is within the proximal promoter of the telomerase reverse transcriptase (TERT) gene, first demonstrated as frequently mutated in melanoma, and subsequently in a variety of other malignancies." (PMID 27611953, 2016). "Recently, −124C > T and −146C > T somatic mutations at the TERT promoter were discovered in melanoma; a reporter assay showed that these mutations increased TERT transcription activity by creating a binding motif for transcription factor ETS2 in multiple cell lines." (PMID 26575952, 2016). "An important insight into the mechanism of TERT reactivation was discovered in 2013, when two independent studies identified recurrent somatic mutations in the core promoter of TERT genes in different melanoma samples." (PMID 27403431, 2016). "That predicted telomere score has been established as a strong risk factor for melanoma in the general population, and germline POT1, TERT and other shelterin complex gene mutations have been found in melanoma families, suggests that telomere function is critical in melanoma susceptibility." (PMID 26433962, 2016). "The acquisition of TERT promoter mutation in BRAF or NRAS mutated melanoma probably allows the re-expression of TERT leading to the immortalization process on path to melanoma development, together with other alterations such as inactivation of cyclin-dependent kinase inhibitor 2A (CDKN2A)." (PMID 27449293, 2016). "That result suggested that ETS1 could be the transcription factor linking the activation of the MAPK pathway to the expression of TERT in melanoma cell lines harboring TERT promoter mutations." (PMID 27449293, 2016). "To confirm that this method could identify regions known to be biologically important in melanoma, we examined those hotspots with high numbers of mutations and a high proportion of samples; pleasingly this identified TERT and BRAF SNVs as striking outliers." (PMID 27611953, 2016). "TERT promoter mutations are known to be more common in BRAF or NRAS mutated tumors compared to WT melanomas and trend towards worse OS, however the role of TERT mutations in MBM is also unknown." (PMID 26597176, 2015). "The TERT SNP alleles associated with longer telomeres are associated with higher risk of melanoma." (PMID 25077817, 2015). "The mutations in the DPH3 promoter tend to co-occur with TERT promoter mutations more frequently than expected by chance in melanoma (OR = 3.0, 95% CI 1.4 - 6.4, P = 0.006), BCC (OR = 3.4, 95% CI 1.5 - 7.6, P = 0.003) and SCC (OR = 4.3, 95% CI 0.9 - 20.2, P = 0.06)." (PMID 26416425, 2015). "Interestingly, in our original series of pediatric melanoma, we found a hot-spot TERT-p mutation in the single patient with SM who died of disease but in no other patients with spitzoid tumors who had favorable outcomes." (PMID 26061100, 2015). "TERT promoter mutations were recently discovered in melanoma by next generation sequencing." (PMID 25042800, 2014). "In melanomas with TERT promoter mutations, TERT is stably expressed at a high level." (PMID 24937153, 2014).
melanoma (continued). "Given the recent finding that the UV-related TERT promoter mutation, up-regulating TERT gene transcription, widely occurs in malignant melanoma and other skin cancers, we sought to ask whether this was also the case in MCC." (PMID 25301727, 2014). "We identified somatic mutations within the promoter of TERT in 9 of 13 (68%) melanoma cases." (PMID 25393105, 2014). "However, alleles in the telomerase-coding gene TERT that predispose to shorter telomere length, increase the risk of most cancers but are protective for melanoma (available online)." (PMID 25231748, 2014). "A recent study has shown that the TERT-CLPTM1L locus is also associated with melanoma risk." (PMID 23889843, 2013). "In addition, a meta-analysis including data from an Australian case-control study showed that TERT–CLPTM1L variants do influence melanoma risk, albeit with a relatively small effect size." (PMID 23393597, 2013). "The TERT locus (at 5p15.33) was found associated with melanoma risk." (PMID 24416617, 2013). "The oncogenic role of TERT is further supported by findings in uveal melanoma, where activating promoter mutations have been identified in primary tumor samples, reinforcing its importance in melanoma pathogenesis through telomerase reactivation and cellular immortality." (PMID 40981345, 2025). "Interestingly, 70% of melanomas and many other solid tumors have somatic TERT promoter mutations." (PMID 40563586, 2025). "Notably, both MBM-PDO cultures from BRAF wild-type melanomas also had TERT promoter mutations." (PMID 39204387, 2024). "Here, we hypothesized that TERT promoter revertant mutations would inhibit melanoma growth." (PMID 35053139, 2022). "Furthermore, TERT promoter mutations are associated with visceral spreading in melanoma of the trunk, which may explain that trunk melanoma can skip local metastases by promoting visceral transmission." (PMID 35903534, 2022). "We wanted to explore whether anchored multiplex PCR technology, which enables the enrichment of target DNA using gene specific primers located at only one end of the DNA, could concurrently detect TERT promoter mutations and driver oncogenes in melanoma liquid biopsies." (PMID 35494035, 2022). "Therefore, telomerase inhibition may be a future intervention for melanoma with TERT promoter mutations, and more experiments are needed to further explore and verify." (PMID 35903534, 2022). "Therefore, the genetic duet of BRAF V600E and TERT promoter mutations represents an effective therapeutic target in cancer, so that combined targeted therapy may improve the overall survival of melanoma patients with TERT promoter mutations." (PMID 35903534, 2022). "Notably, we found that male patients with TERT mutation may be more likely to benefit from immunotherapy, especially for melanoma." (PMID 32915164, 2020). "We also found 99 patients who received anti‐CTLA4 treatment, including 75 patients with melanoma (43 with TERT mutations and 32 with TERT wild type), 20 patients with breast cancer (all with TERT wild type), and four patients with other cancer types (also TERT wild type)." (PMID 32810393, 2020). "However, the results showed that only patients with melanoma with TERT mutation could more likely benefit from anti‐CTLA4 treatment." (PMID 32810393, 2020). "Notably, we found that male patients with TERT mutation may be more likely to benefit from immunotherapy (p = 0.006), especially for melanoma (p < 0.001)." (PMID 32915164, 2020). "Therefore, in trunk primary melanomas, due to their high risk of progression to visceral sites, we encourage somatic TERT mutation analysis at diagnosis to identify those patients who would potentially benefit from a more intensive follow-up protocol and a prompt initiation of therapy." (PMID 30934988, 2019).
melanoma (continued). "Therefore, we encourage TERT promoter mutation analysis at diagnosis in the primary melanomas of the trunk since their progression will likely occur in a visceral site in the majority of cases and patients would potentially benefit from early detection and prompt treatment." (PMID 30934988, 2019). "Furthermore, in A375 and M74 melanoma cells, the mutation of TERT promoter, could be associated with increased TERT expression and cell survival." (PMID 31801187, 2019). "Furthermore, the association between TERT promoter mutations and trunk site is supported by evidence that melanomas occurring in intermittently sun-exposed skin as trunk site displayed an increased prevalence of TERT promoter mutations compared with melanomas occurring in sun-protected areas." (PMID 30934988, 2019). "In addition to these two common hotspots identified on chromosome 5: 1,295,228 C > T (C228T) and 1,295,250 C > T (C250T), the tandem mutations of 1,295,228/1,295,229 CC > TT (C228T/C229T) and 1,295,242/1,295,243 CC > TT (C242T/C243T) have also been reported in melanoma with TERT promoter mutation." (PMID 29222734, 2018). "The highly recurrent mutations in the promoter of TERT are found in over 50 cancer types, including papillary thyroid carcinoma, hepatocellular carcinoma, epithelioid glioblastoma, bladder cancer, malignant pleural mesothelioma, melanoma, are the most common mutation in many cancers." (PMID 28726783, 2017). "It is speculative but TERT could predispose to a broader range of cancers than melanoma." (PMID 26433962, 2016). "In addition, co-segregation with a germline mutation in TERT promoter has been observed in an informative melanoma-prone family, suggesting that this gene may also act as a rare high-penetrance melanoma susceptibility gene." (PMID 26322273, 2015). "TERT-p mutations may be acquired late during multistep melanoma development." (PMID 26061100, 2015). "Among those reported to occur at high frequency, particularly in melanoma, are the C228T and C250T mutations which occur close to the transcriptional start site and introduce gain of function binding sites for Ets family transcription factors resulting in increased TERT promoter activity." (PMID 24550717, 2014). "Using immunohistochemistry, we examined 36 cases of thin melanomas and 39 cases of melanocytic nevi for TERT protein expression." (PMID 40361989, 2025). "Mutation frequencies also vary across specific anatomical sites, with head and neck melanomas more often showing mutations in NRAS and TERT promoters, and genitourinary or anorectal melanomas showing KITKIT mutations." (PMID 41295253, 2025). "Other clinical trials, phase I or II, have illustrated that dendritic cells loaded with TERT p540 peptide sustain the clinical response of prostate, breast, lung cancer, and melanoma patients." (PMID 40563586, 2025). "The TERT staining in melanoma was present in a higher percentage of the cells, with higher intensity, and only at the cytoplasmic level compared to melanocytic nevi." (PMID 40361989, 2025). "Melanoma arises from somatic mutations that trigger the malignant transformation of melanocytes, including mutations in BRAF, NRAS, TERT, PI3K, and KIT, among other genes." (PMID 40429816, 2025). "The melanoma patients whose tumours stained positive for TERT in over 50% of the cells were older (median = 64 years) than those with melanomas that stained in under 50% (median = 51 years)." (PMID 40361989, 2025). "Previous research suggests that many lesions diagnosed as an SM or AST, that developed distant metastases and resulted in a fatal outcome, were actually conventional melanomas harboring BRAF or NRAS mutations, frequently accompanied by TERT-p alterations." (PMID 40227833, 2025).
melanoma (continued). "Still, they observed an increase in mean TERT expression from acquired nevi to dysplastic nevi and melanomas." (PMID 40361989, 2025). "BRAF, NRAS, or NF1 mutations can co-occur with C/T mutations in the promoter region of the telomerase reverse transcriptase (TERT) gene, which are frequently observed in melanoma, occurring in 30–85% of cases depending on disease stage." (PMID 39859576, 2025). "Further, several genes like TERT, POT1, ACD, and TERF21P, which all have functions related to telomere maintenance and stability, have been identified as melanoma susceptibility genes." (PMID 40072281, 2025). "When there are borderline features, molecular assessment for the presence of additional mutations, such as CDKN2A or TERT-p, and chromosomal CNA can be helpful in differentiating low-CSD melanomas from intermediate lesions." (PMID 38247727, 2024). "Preexisting anti-TERT Th1 responses have been associated with better response rates, longer PFS, and OS in patients with melanoma treated with ICIs." (PMID 38695555, 2024). "Given the patient’s prior history, the splenic mass was diagnosed as the metastasis from previous melanoma, which was confirmed by NGS findings of TERT mutations among others." (PMID 39258061, 2024). "In melanoma, the TERT promoter contains two highly recurrent somatic SNVs (chr5:1,295,228; C > T, and chr5:1,295,250; C > T) allowing the binding of the ETS TF." (PMID 38902506, 2024). "The TERT-promoter mutations upregulate telomerase activity, allowing cancer cells to survive, and prior studies have shown TERT-mutant melanomas to have earlier recurrence and progression, as well as resistance to treatment." (PMID 38158497, 2024). "In conclusion, our study suggests additional non-coding drivers beyond the well-characterised TERT promoter in melanoma." (PMID 39367275, 2024). "Only a minor fraction of acral melanomas bear point mutations in BRAF and TERT, which are common in sun-exposed melanomas." (PMID 39034322, 2024). "In our cohort, TERT stood out as the most frequently altered gene with 26 of 37 (70.3%) melanomas harboring TERT alterations." (PMID 39034322, 2024). "Additional molecular oncogenic alterations (CDKN2A and TERT-p) are necessary for the development of DPN-like melanomas." (PMID 38247727, 2024). "Amidst the vast genomic landscape, the promoter region of the telomerase reverse transcriptase (TERT) gene emerges as a significant focal point in melanoma." (PMID 39078811, 2024). "Germline mutations of CDKN2A, CDK4, TERT, and POT1 genes have been identified as high-risk factors for melanoma susceptibility, whereas MC1R (melanocortin 1 receptor) polymorphic variants are reported in 60.5–82.1% of melanoma." (PMID 38473275, 2024). "The authors report that TERT mutations were identified in 70% of PLA-positive lesions diagnosed as melanoma and only 4% of severely dysplastic nevi and non-melanoma lesions." (PMID 38339333, 2024). "Melanocytic nevi, typically benign, can evolve into melanoma through mutations, primarily BRAFV600E in common nevi and various mutations in MAPK signaling, the TERT promoter, and CDKN2A in dysplastic nevi." (PMID 38474231, 2024). "As these effects were described predominantly in non-cancer tissues, we aimed to identify potential mitochondrial correlates of TERT expression in cancer and, specifically, in melanoma." (PMID 37418389, 2023). "Recent data showed that TERT promoter mutations, in BRAF-mutant melanoma cell lines, were associated with sensitivity to BRAF and MEK inhibitors highlighting a link between the expression of telomerase and sensitivity to targeted therapy." (PMID 37296851, 2023).
melanoma (continued). "Our study findings support the inclusion of TMG (POT1, TERF2IP, ACD, and TERT) on genetic testing panels when a familial melanoma case exhibits spitzoid morphology in at least 25% of the tumor cells." (PMID 36876055, 2023). "Altogether, these results suggest that the overexpression of TERT was associated with increased resistance to BRAF and MEK inhibition in BRAF-mutated melanoma cell lines by a mechanism involving the reactivation of the MAPK pathway." (PMID 37296851, 2023). "A number of melanoma recurrent mutations have been reported in the literature in several genes including KIT, TERT, MAP2K1 and MAP2K2, RAC and PPP6C." (PMID 36765773, 2023). "Preclinical studies have shown that inhibiting telomerase activity or TERT expression can lead to telomere shortening, cellular senescence, and reduced melanoma cell proliferation." (PMID 37504268, 2023). "In the context of TERT expression, 17 genes were consistently upregulated with TERT expression in all seven bulk RNA-seq cohorts, comprising melanoma and a cross-entity cancer cohort, as well as a cross-entity cell line cohort." (PMID 37418389, 2023). "Although less frequent than UV-related melanomas, 9–41% of acral melanomas and 30% of mucosal melanomas exhibit TERT alterations." (PMID 37239381, 2023). "We also observed upregulation of TERT expression with all hypoxia scores in the melanoma cohort and with Buffa hypoxia scores across entities (Wilcoxon p = 7.43e-22)." (PMID 37418389, 2023). "Two studies showed intratumoral heterogeneity within the same melanoma samples for BRAF and TERT mutation status using different micro-dissected regions of the same sample." (PMID 38003476, 2023). "TERT expression in melanoma can therefore be a new biomarker for resistance to MAPK inhibitors as well as a novel therapeutic target." (PMID 37296851, 2023). "We also identified spitzoid morphology in melanomas from individuals with variants in TMG other than POT1 (TERF2IP, ACD, and TERT)." (PMID 36876055, 2023). "Subsequent modifications in the TERT promoter and other genes lead to the progression of nevus into melanoma." (PMID 36834954, 2023). "Mutational profile of mucosal melanomas is known to differ from their cutaneous counterparts, suggesting a different pathway in the pathogenesis: They harbor lower BRAF and TERT, and relatively higher NRAS and KIT mutation frequencies." (PMID 35642348, 2023). "In the case of sporadic melanomas, comprising more than 90% of all melanomas, several susceptibility loci acting as moderate (BAP1, TERT, POT1, ACD, TERF2IP and MITF) or low penetration genes have been identified." (PMID 36765773, 2023). "We confirmed that these TERT correlates were mostly tumor cell-specific genes within melanoma, as 15 genes were predominantly expressed in malignant tumor cells in our scRNA-seq data." (PMID 37418389, 2023). "It is therefore clear that TERT expression can contribute to resistance to targeted therapies independently of its telomere maintenance activity; however, further studies are necessary to determine which pathways are modulated by TERT in human melanoma." (PMID 37296851, 2023). "Due to the high prevalence of TERT promoter aberrations in various melanoma subtypes, it is a potential target for melanoma treatment." (PMID 37239381, 2023). "We demonstrated that TERT overexpression in BRAF-mutated melanoma cells reduced sensitivity to BRAF and MEK independently of TERT’s telomer maintenance activity." (PMID 37296851, 2023). "Here, metastatic melanomas showed higher TERT expression if they originated from thinner primaries, prompting the question of increased TERT expression in efficient early metastasis." (PMID 37418389, 2023). "Targeting telomerase and the TERT gene has been explored as a potential therapeutic strategy in melanoma." (PMID 37504268, 2023). "Germline mutations that significantly increases the life-time risk of developing melanoma include CDKN2A, CDK4, BAP1, TERT, MITF, MC1R, and POT1." (PMID 38076247, 2023).